RO60 (Ro60, Y RNA binding protein)
Diseases named in the same sentence as RO60 in open-access papers (continued):
Sharing a sentence is not in itself a finding about the gene and the disease.
Sjögren’s syndrome (continued). "Autoantibodies against the RNA-binding protein Ro60 can be found in SLE as well as Sjögren’s syndrome patients; however, the role of Ro60 in the pathogenesis of these diseases remains unclear." (PMID 33445593, 2021). "In the Ro52+Ro60+ group, primary Sjögren's syndrome was the most frequent diagnosis." (PMID 30915082, 2019). "Interestingly, patients with the “triad” Ro52, Ro60 and La Ab were even more likely to have Sjögren's syndrome than the double positive patients (53.2% vs. 31.3%, p = 0.01)." (PMID 30915082, 2019). "In Sjögren’s syndrome patients, anti-Ro52 antibodies often coexist with anti-Ro60." (PMID 30261673, 2018). "In a study that proved Sjögren’s syndrome autoantigen RO60/SS-A binds Alu RNAs, transfection of the bound Alu motif into peripheral blood cells stimulated proinflammatory cytokine secretion, while IFN-α treatment of RO60-null lymphocyte cells activated Alu transcription." (PMID 27525044, 2016). "Non-salivary gland initiated immune response with associated loss of gland activity are reported in other animal models with primary Sjögren’s syndrome like phenotypes such as the thyroid specific IL-12 transgenic mouse and the Ro60 peptide immunization study." (PMID 24551030, 2014). "Notably, the association between anti-Ro52 and Sjögren’s syndrome was not identified until 2018, in which anti-Ro52 and anti-Ro60 were analyzed separately in relation to ILD." (PMID 37667402, 2023). "RNY1 is a regulator of the protein Ro60, which is a common autoantigen in both SLE and Sjögren’s syndrome." (PMID 41595515, 2026). "Ro60 is an autoantigen that can bind to RNAs; studies have detected the presence of Ro60-specific antibodies in autoimmune diseases such as SLE, neonatal lupus, or Gougerot-Sjögren syndrome." (PMID 35909659, 2022). "The proteins Ro60 (TROVE2, SSA) and La (SSB), which are common auto-antigens in autoimmune diseases (like systemic lupus erythematosus and Sjögren’s syndrome, were identified as the major antigens facilitating the association with these small ncRNAs." (PMID 24970161, 2013). "In Sjögren’s syndrome, Sjögren’s syndrome Antigen A (SSA)/Ro60-reactive T cells can be activated by peptides originating from oral and gut bacteria, and thus may be involved in disease progression." (PMID 39619660, 2024). "Autoantibodies to SS-A/Ro are part of the current classification criteria for Sjogren’s syndrome (SjS), though the criteria do not distinguish between Ro60 and Ro52/TRIM21 antibodies." (PMID 35371074, 2022). "Anti-Ro60 (69.5%), anti-Ro52 (66.9%), and anti-La (49.5%) antibodies were prevalent in Sjögren’s syndrome [no antibodies were detected in 58/279 (20.8%) patients], while in 133 SSc patients, anti-centromere (CENP-B) accounted for 50.8% and anti-Scl70 for 34.1%." (PMID 36564813, 2022). "None of these two patients had concomitant anti-Ro60 abs or clinical evidence of sicca syndrome." (PMID 32308974, 2020). "Altogether, this suggests a model, in which the aberrant sensing of Alu transcripts in the absence of Ro60, for example by TLR7, contributes to endogenous immune activation in autoinflammatory diseases such as Sjögren’s syndrome or SLE." (PMID 33445593, 2021). "In a later publication about the clinical practice of the Sjögren’s syndrome, it is stated that only anti-SS-A/Ro60 antibodies have to be considered, because isolated anti-Ro52/TRIM21 antibodies are not specific for the Sjögren’s syndrome." (PMID 32127033, 2020).
autoimmune disease (34 papers, 2009 to 2025). A disorder resulting from loss of function or tissue destruction of an organ or multiple organs, arising from humoral or cellular immune responses of the individual to their own tissue constituents. "Ro60 is an extractable nuclear antigen, and serum Ro60 autoantibodies are common diagnostic markers for various autoimmune diseases, including SjD, SLE, SSc, inflammatory myositis, and neuropsychiatric SLE." (PMID 39062948, 2024). "Previous literature also supports the observation that Ro52 and Ro60 seropositivity is one of the earliest markers of risk for future manifestation of other autoimmune diseases." (PMID 30913258, 2019). "The sequences combine with inflammatory protein RO60, correlated with autoimmune diseases, to form a complex named ‘RoRNP’." (PMID 40863727, 2025). "Ro60 and La, which autoantibodies are detected in the serum of autoimmune disease patients, are Y RNA-binding proteins." (PMID 38997262, 2024). "In keeping with the broader observation that serum autoantibodies foreshadow the development of autoimmune diseases, Ro60 autoantibodies can be detected years before the clinical onset of autoimmune diseases." (PMID 39062948, 2024). "Y RNAs form Ro-RNP complex with Ro60, which has been reported to be one of the common autoantigens observed in autoimmune diseases, to regulate the cytoplasmic localization of Ro protein by masking the nuclear localization signal of the protein." (PMID 38997262, 2024). "The human genome has four functional Y-RNAs (RNY1, 2, 3, and 5), which are a class of small noncoding RNAs that bind and regulate Ro60, a protein involved in the cell’s response to stress and one identified as an autoantigen in autoimmune diseases." (PMID 38308367, 2024). "Some studies that correlate sCP and autoantibodies in autoimmune diseases showed that high levels of sCP have been associated with positive autoantibodies (Ab-anti-dsDNA, anti-SSA, anti-Ro60, AchR-Ab, Musk-Ab, LRP4-Ab, levels of MPO and PR3...)." (PMID 38792945, 2024). "YRNAs are short 80–110 nt ncRNAs, first identified in the early 1980s as an RNA component of the soluble Ro60 ribonucleoprotein particle found in the blood of patients with autoimmune diseases." (PMID 30634628, 2019). "Are these data epiphenomenal or do they really play a role in the induction of anti-Ro52 or anti-Ro60 in SSc, other AIRDs or indeed in other autoimmune diseases?" (PMID 30581434, 2018). "Although no homologies between the predicted epitopes of the NIS transporter and those of TPO and Ro60 were detected in this study, the T-cell epitopes of NIS could bind to the same HLA class II alleles that predispose to both autoimmune diseases." (PMID 41516079, 2025). "Preventing the development of Ro60 reactivity in T and B cells could be a therapeutic target for autoimmune diseases." (PMID 40142449, 2025). "Characterising Ro60 epitopes may help to understand the immune response and develop targeted therapeutic approaches for autoimmune diseases where Ro60 is an autoantigen." (PMID 39062948, 2024). "It will be important to uncover whether and how Ro60 RNP complexes promote TLR7 signalling to drive pathogenesis in other autoimmune diseases." (PMID 39062948, 2024). "Anti-SS-A antibodies such as Ro52 and Ro60 are often used in autoimmune disease diagnosis." (PMID 35002713, 2021). "Recent scientific reports emphasize that testing for autoantibodies against anti-Ro52/anti-Ro60 peptides may guide diagnosis, classify clinical manifestations in disease entities and define prognosis in certain autoimmune disorders." (PMID 34575305, 2021). "Finally, IFN-β1b or betaseron, a common therapy for RRMS, but not other autoimmune diseases, restores the balance of polyadenylated structural RNAs to normal and reverses the loss of Ro60 and La that is seen in RRMS." (PMID 25885816, 2015).
autoimmune disease (continued). "In autoimmune diseases such as SjD, SLE, RA, and systemic sclerosis (SSc), Ro60 autoantibodies often co-exist with autoantibodies targeting Ro52 (also called TRIM21) and La/SSB." (PMID 39062948, 2024). "As for Ro60, mice lacking its encoding genes do tend to develop autoimmune disorders, in which it is possible to find antibodies directed against ribosomes and chromatin; glomerulonephritis were observed as well, suggesting the role of Ro60 in preventing systemic autoimmune diseases." (PMID 34827064, 2021). "Autoantibodies to SS-A2/Ro60 are found in more than 60% of SS patients and 25–40% of SLE patients, as well as in patients affected by other autoimmune diseases." (PMID 31435505, 2017). "Among autoantibodies in autoimmune disease, the Ro/SSA (made up of Ro60 and Ro52) antibody is the most common one to extractable nuclear antigens." (PMID 25379317, 2014). "Antibodies to Ro-52 (a tripartite motif protein/TRIM) can be found independent of antibodies to Ro-60 (a small cytoplasmic ribonucleoprotein/scRNP) in certain autoimmune disorders." (PMID 25379317, 2014). "However, anti-Ro52 autoAbs can be present without ever anti-Ro60 reactivity in many autoimmune diseases." (PMID 30581434, 2018). "Thus, both TROVE2 and SSB transcripts and Ro60 and La proteins were profoundly diminished in RRMS and these mRNA and protein expression differences were not seen in several other autoimmune diseases." (PMID 25885816, 2015).
Autoimmunity (22 papers, 2013 to 2026). The occurrence of an immune reaction against the organism's own cells or tissues. "While the lack of correlation between ESSDAI and sMer levels was perplexing and could be due to the small sample size, the correlations we did observe regarding Ro60 and SG infiltration reinforce the association between Mer inactivation and the development of autoimmunity in SjS." (PMID 34575873, 2021). "In particular, RO60 has been extensively investigated with respect to autoimmunity and intracellular sensing, and the open/closed system of the central hole in the doughnut-like steric structure is a putative target." (PMID 30273347, 2018). "As RNY1 assists Ro60 in its function, depletion of RNY1 might attenuate the protective effect of Ro60 and be an indication of autoimmunity." (PMID 41595515, 2026). "The summation of our findings and the literature suggests that subclinical Ro52 and Ro60 autoantibodies may contribute early in the pathophysiology of autoimmunity in certain subpopulations." (PMID 30913258, 2019). "For Ro60 and various bacteria, a shared group of highly conserved amino acids which contribute an essential role in the folding of proteins may promote clinical autoimmunity." (PMID 35704681, 2022). "Nevertheless, this mechanism may be relevant in autoimmunity only if the rate of citrullination is high as consequence of cell stress that together with an appropriate class II molecule to handle the Ro60 as autoantigen could result in an autoreactive response." (PMID 29318161, 2017). "Antibodies to Ro60 antigens are called anti-SSA/Ro and patients who express Ro60 antibodies in most cases are diagnosed with autoimmune conditions, including SS." (PMID 32560266, 2020). "After immunizing rabbits with either HNE-modified or unmodified SS-A2/Ro60, they observed that autoimmunity was established faster and more strongly in animals immunized with HNE-modified SS-A2/Ro60." (PMID 24027536, 2013). "Additional interactions between Ro60-RNP complexes and B cells can occur via complement receptors, which can reduce B-cell activation thresholds, whilst FcγRIIB engagement dampens B-cell activation and autoimmunity." (PMID 39062948, 2024). "The isolated anti-Ro52/TRIM21 group tended to be older compared to the anti-Ro52/TRIM21 combined with anti-Ro60 and/or -La, so it is surprising that additional time did not manifest in proportionally more clinical autoimmunity." (PMID 35871174, 2022). "This is likely due to isolated anti-Ro52/TRIM21 being associated with a variety of immunological and non-immunological conditions compared to anti-Ro60 and anti-La being more specific for autoimmunity." (PMID 35871174, 2022).
myositis (10 papers, 2009 to 2025). "Although not well-described in the setting of myositis, work from our animal model of HRS (histidyl-tRNA synthetase)-induced myositis suggests that anti-Ro60 antibodies may also be linked to specific MSAs such as anti-HRS/Jo-1." (PMID 38895121, 2024). "The expression pattern of receptors for BAFF on B and plasma cells in muscle suggests a local role for BAFF in autoantibody production in muscle tissues of patients with myositis who have anti-Jo-1 or anti-Ro52/anti-Ro60 autoantibodies." (PMID 25301447, 2014). "Our data indicate a possible local role for BAFF in muscle tissue from patients with myositis, particularly in a subset of patients with anti-Jo-1 or anti-Ro52/anti-Ro60 autoantibodies." (PMID 25301447, 2014). "On the other hand; several groups demonstrated the importance of separate detection of anti-Ro52 and anti-Ro60 antibodies when considering the diagnosis and, in particular, of patients with myositis." (PMID 23304190, 2012). "In a recent study, the frequency of anti-Ro52 antibodies was similar to that of anti-Ro60 in all groups but the myositis (35.4% versus 0.0%, P < 0.001) and SSc (19.0% versus 6.0%, P < 0.005) cohorts using the consensus of three different laboratory methods." (PMID 23304190, 2012). "Anti-Ro-52/TRIM21 is significantly more prevalent in SSc and myositis than anti-Ro-60, while isolated anti-Ro-52/TRIM21 may be found in up to 37% of patients with myositis, often in correlation with anti-Jo-1 reactivity." (PMID 26161084, 2015). "Together, these observations may imply that BAFF and type I IFN could interact and play a role in the pathophysiology of myositis with anti-Jo-1 and/or anti-Ro52/anti-Ro60 autoantibodies." (PMID 25301447, 2014). "Lastly, inspection of the five ATPase seropositive DM patients revealed that they were all co-positive for Ro60, as well as one additional autoantigen, suggesting that the anti-gastric autoantibodies in myositis reflected existing high levels of auto-reactivity." (PMID 24602337, 2014). "Anti-Ro52 antibodies are common in patients with antisynthetase antibodies, and anti-Ro60 and anti-La/SSB may be seen with other myositis-specific antibodies." (PMID 36899995, 2023). "In the same study, the percentages of anti-Ro52 antibodies detected without anti-Ro60 antibodies also varied from 5.4% in childhood SLE to 35.4% in the myositis group." (PMID 23304190, 2012). "Through our established model of HRS-induced myositis that has allowed us to explore immunopathogenic mechanisms of the anti-synthetase syndrome, we have demonstrated that mice immunized with recombinant HRS develop antibodies against additional autoantigens including both Ro52 and Ro60." (PMID 38895121, 2024). "As shown in our model of HRS-induced myositis, there is compelling evidence that autoantibodies targeting HRS, Ro52, and Ro60 are independently generated in BALF as well as serum—suggesting that the lung microenvironment may represent a primary site for breakdown of immune tolerance." (PMID 38895121, 2024).
neonatal lupus (5 papers, 2006 to 2022). "The objective of this study was to identify putative Ro52/60-kDa Ro/SSA antigen (Ro60) epitopes associated with neonatal lupus and congenital heart block." (PMID 16356190, 2006). "In neonatal lupus erythematosus (NLE), autoantibodies against ribonucleoproteins 48-kDa SSB/La, 52-kDa SSA/Ro (Ro52) and 60-kDa SSA/Ro (Ro60) have received more attention, since they have been shown to be strongly associated with autoimmune responses involved in symptoms like CHB." (PMID 17445258, 2007).
rheumatic diseases (5 papers, 2016 to 2025). "Overlap between rheumatic disease–associated autoantibodies, including anti‐Ro60 and RF, have been linked to ERE activity." (PMID 39681508, 2024). "Ro60 RNP is a target of autoantibodies in patients with some rheumatic diseases, potentially contributing to their initiation and progression." (PMID 40725121, 2025). "Ro60 is a clinically important target of autoantibodies in patients with rheumatic diseases, such as SS and SLE." (PMID 36741231, 2023). "In fact, PDC proteins have molecular weights around 55 kDa (E3BP and E2), similar to autoantigens such as Ro60, Ro52, or Jo-1 that are common in rheumatic diseases; thus, it is necessary to confirm AMA positivity by IP-WB." (PMID 35296099, 2022).
Arthritis (4 papers, 2014 to 2024). Inflammation of a joint. "Similar trends are apparent for mechanic’s hands and arthritis/arthralgia; in the case of classic DM rashes, the presence of anti-Ro60 antibodies is associated with diminished frequency of this extra-muscular complication, even within the anti-Ro52 antibody-positive subset (p>0.05)." (PMID 38895121, 2024). "Specific SLE subsets were linked to the upregulation of different subtypes of circulating IFNs: high IFN-γ to arthritis, nephritis and anti-Ro60 antibodies and high IFN-α to mucocutaneous engagement and anti-Ro52 and anti-La antibodies." (PMID 31036046, 2019). "High levels of IFN-γ were associated with high disease activity, and clinical features such as active arthritis, anti-Ro60 and low complement, as well as active nephritis." (PMID 31036046, 2019). "By comparison, patients with arthritis, rash, Raynaud's phenomenon and anti- Ro60/SS-A autoantibodies did evolve to SLE." (PMID 24705829, 2014). "Besides, the overlap between high IFN activity and IFN-γ was observed among patients with arthritis (27%) and low complement (25%) and carrying anti-dsDNA (16%), anti-Sm (33%) or anti-Ro60 (17.5%) antibodies." (PMID 31036046, 2019). "Similar to anti-RO60, anti-MOV10 were higher in SLE patients with anti-dsDNA antibodies, in those with arthritis, and in those with elevated type I interferons." (PMID 39606792, 2023).
leukopenia (4 papers, 2014 to 2024). "Prior studies have shown that patients with anti-Ro52 and anti-Ro60 antibodies have higher rates of leukopenia and increased production of CXCL10, potentially contributing to a lowered vaccine efficacy in this subgroup." (PMID 38456511, 2024).
rheumatoid arthritis (4 papers, 2022 to 2025). A chronic, systemic autoimmune disorder characterized by inflammation in the synovial membranes and articular surfaces. "This study aimed to evaluate the clinical and immunological significance of anti-Ro52/TRIM21 and anti-Ro60/SSA antibodies in rheumatoid arthritis (RA), particularly the association of dual antibody positivity with disease severity, systemic manifestations, and therapeutic resistance." (PMID 40901469, 2025). "In this study, we conducted a comprehensive evaluation of the clinical and immunological profiles of rheumatoid arthritis (RA) patients stratified by anti-Ro52 and anti-Ro60 antibody status." (PMID 40901469, 2025). "Furthermore, the prevalence of difficult-to-treat rheumatoid arthritis (D2T-RA) was significantly higher in the Ro52+/Ro60+ (13%) and Ro52+/Ro60− (11%) groups compared to the Ro52−/Ro60− group (3.5%, p = 0.006), suggesting a more refractory disease course in these antibody-positive subgroups." (PMID 40901469, 2025). "An autoimmune renal screen performed showed strongly positive antinuclear antibodies (ANA) and anti-Sjögren's-syndrome-related antigen A (SS-A/Ro60) which were in keeping with her history of rheumatoid arthritis rather than an alternative autoimmune pathology." (PMID 40698215, 2025).